MTOR (mechanistic target of rapamycin kinase)
Diseases named in the same sentence as MTOR in open-access papers (continued):
Sharing a sentence is not in itself a finding about the gene and the disease.
Insulin resistance (continued). "Thus, activation of the mTOR pathway leading to the down-regulation of IRS-mediated signals is a negative feedback mechanism which may be involved in the development of insulin resistance." (PMID 26474286, 2015). "Although this feedback effect of S6K has been proposed to participate in the etiology of insulin resistance, it may also act as a mechanism to prevent overactivation of the MTOR pathway in order to allow some autophagy to continue even under nutrient-rich conditions." (PMID 24880909, 2015). "However, recent studies suggest that chronic treatment with mTOR inhibitors like rapamycin may lead to insulin resistance." (PMID 24667246, 2014). "However, evodiamine inhibited insulin-stimulated phosphorylation of mTOR and S6K, leading to suppression of IRS1 serine phosphorylation in adipocytes, suggesting evodiamine acts to improve insulin resistance by repressing activation of mTOR-S6K signaling by insulin." (PMID 24391749, 2013). "Proteomics validated higher insulin resistance in STBs alongside elevated insulin secretion, AMPK, mTOR, and MAPK pathway activities." (PMID 41556081, 2026). "BCAA metabolic disruption can induce insulin resistance and autophagy inhibition through mTOR overactivation, whereas PPAR agonists have been shown to alleviate metabolic imbalances by modulating mTOR activity." (PMID 41460756, 2026). "By regulating key pathways involved in focal adhesion, PI3K/AKT/mTOR signaling, inflammatory response, and lipolysis, FAM20C modulates adipocyte function and contributes to insulin resistance in obesity." (PMID 41148235, 2025). "In addition to the classical mTOR, NF-κB, JNK, and PI3K/Akt pathway, a COX-2-dependent mechanism has also been found to modulate macrophage polarization in the development of post-incisional pain, obesity-associated insulin resistance and Hirschsprung disease-associated Enterocolitis." (PMID 40357333, 2025). "For instance, in the state of insulin resistance, hyperinsulinemia occurs, activating the PI3K/Akt/mTOR/S6R signaling pathway, which facilitates glucose uptake and utilization by tumor cells, providing energy for cancer cell proliferation." (PMID 40895039, 2025). "In a GDM rat model, inhibition of miR-873, which targeted IGFBP2, was shown to regulate insulin resistance and alleviate myocardial injury by activating the PI3K/AKT/mTOR signaling pathway, thereby mitigating the progression of GDM." (PMID 40453589, 2025). "For instance, insulin resistance and hyperinsulinemia activate oncogenic pathways, including PI3K-Akt-mTOR, which promote tumor cell proliferation and angiogenesis." (PMID 40291918, 2025). "For example, the activation of inflammatory mTOR and TLR pathways is likewise fundamental to adipose-driven insulin resistance." (PMID 41007744, 2025). "Insulin resistance is also affected through AMPK and the mammalian target of the rapamycin/p70 ribosomal S6 kinase (mTOR/p70 S6K) signaling pathways." (PMID 39795155, 2024). "For insulin resistance in skeletal muscle, AKT has been documented to primarily exert its effects on the mammalian target of rapamycin (mTOR)." (PMID 38368351, 2024). "Firstly, insulin resistance leads to hyperinsulinemia, which in turn motivates signaling pathways (Ras/MAPK and PI3K/Akt/mTOR), NF-κB nuclear translocation, and gene transcription from cancer-related genes." (PMID 38279158, 2024). "KEGG enrichment analysis showed that these genes were significantly enriched in the mTOR signalling pathway, metabolic pathway, fatty acid metabolism, and mTORComplel1-S6K1 signalling pathway, which is directly related to insulin resistance." (PMID 38396669, 2024).
Insulin resistance (continued). "Insulin resistance induces hyperinsulinemia and increases the level of insulin-like growth factor, which can activate the Akt/S6K/PI3K/mTOR signaling pathway in cancer." (PMID 38981909, 2024). "This study aimed to evaluate the role of mTOR in patients with T2DM, and its relationship with insulin resistance and microvascular complications." (PMID 39261960, 2024). "The current work shows, for the first time, that kiwi extract prevents obesity-induced insulin resistance through controlling insulin signaling pathway parameters such as PI3K, AKT, and mTOR." (PMID 37762060, 2023). "Herein, we observed that LDR strongly inhibited HFD-induced insulin resistance through PYCR1 activation to regulate insulin signalling, which is consistent with a previous report that inhibition of Akt/mTOR can induce insulin resistance." (PMID 36088469, 2022). "Among these pathways, thyroid hormone, insulin resistance, HIF-1, mTOR, and AMPK signaling pathways were found to be closely associated with NAFLD." (PMID 36506575, 2022). "In addition, side effects associated with the mTOR inhibitor rapamycin for DKD, such as hyperglycaemia, insulin resistance and dyslipidaemia, have also been reported, which may be related to the metabolic profile of the pancreas and other insulin-resistant tissues, including the liver and muscle." (PMID 36091814, 2022). "By increasing AMPK phosphorylation, HN inhibited mTOR and regulatory element binding protein 1 (SREBP1) to improve insulin resistance and reduce ROS production." (PMID 34177809, 2021). "Studies have shown that the mTOR signaling system is a key pathophysiological basis of PCOS; its overexpression can result in insulin resistance and influence the growth of follicles directly." (PMID 34306142, 2021). "Hyperglycemia and excess FFAs lead to insulin resistance and high levels of ROS resulting in impaired PI3K/AKT/mTOR signaling found in subjects with T2DM." (PMID 33604180, 2021). "Female mTOR-KOPlacenta offspring exposed to HFD also demonstrated worsened glucose intolerance and increased insulin resistance compared with littermate controls." (PMID 34032632, 2021). "In the skeletal muscle and liver, the ATP surplus contributes to insulin resistance through suppression of AMPK and activation of mTOR." (PMID 34987473, 2021). "Other models focused on insulin resistance and aimed to explain the PI3K/MTOR network dynamics following insulin stimulation in healthy and diabetic cells." (PMID 34529665, 2021). "Accordingly, the mTOR/STAT3 pathway controls several important downstream targets, such as HIF-1α and Notch1, which are involved in the regulation of insulin resistance." (PMID 34476533, 2021). "Moreover, the mTOR signalling pathway is highly complex, and its inhibition might result in the undesirable activation or inhibition of other related pathways, leading to the development or worsening of pathologies (e.g. insulin resistance or tumorigenesis)." (PMID 34309456, 2021). "This bioactive molecule can lead to the activation of PI3K/Akt/mTOR insulin receptor substrate 1 (through IRS-1) phosphorylation, promoting insulin signalling pathway activation and thereby reducing insulin resistance." (PMID 34579001, 2021). "One potential mechanism is that elevated BCAAs levels lead to activation of the mTOR/S6K1 pathway and serine phosphorylation of IRS1, contributing to inhibition of insulin-induced PI3K activation and insulin resistance." (PMID 34419103, 2021). "Based on these findings, we propose that the coexistence of chronic LGSI-driven insulin resistance and protein oxidation contribute to the blunted stimulation of PI3K/Akt/mTOR/S6K1 signal transduction pathway, in the aged human skeletal muscle." (PMID 34917235, 2021). "Prolonged activation of mTOR can activate the p70S6K leading to increased phosphorylation of IRS and down regulation of PI3K/Akt, which is involved in insulin resistance." (PMID 32917052, 2020).
Insulin resistance (continued). "Amino acids activate the mTOR/S6K1 pathway, and the activation of mTOR inhibits PI3K that results in insulin resistance." (PMID 33042976, 2020). "Studies have shown that increased phosphorylation/activation of mTOR and/or p70 S6K leads to increased serine phosphorylation of IRS-1 and the development of insulin resistance." (PMID 32230718, 2020). "Many studies showed that hyperphosphorylation/activation of mTOR and p70 S6K, results in increased serine phosphorylation of IRS-1 and contributes towards the development of insulin resistance." (PMID 32664532, 2020). "Insulin resistance induces hyperinsulinemia, which activates PI3K/Akt/mTOR/S6K signaling pathway in cancer." (PMID 32709256, 2020). "Increased activation of muscle mTOR by nutrient overload was shown to lead to increased serine phosphorylation of IRS-1, impaired insulin signaling, and induction of insulin resistance." (PMID 32664532, 2020). "The activated IKKβ not only phosphorylates the serine site of IRS, but also activates mTOR and S6K1 by suppressing the TSC1/2 in adipocytes and hepatocytes, both of which contribute to the induction of insulin resistance." (PMID 31824416, 2019). "Prolonged hyperinsulinemia with excessive nutrition activates the mTOR/S6 kinase pathway, thereby enhancing IRS-1 serine phosphorylation to induce hypothalamic insulin resistance." (PMID 30875909, 2019). "Insulin resistance was regulated by KMOS via the AMPK pathway, the insulin signaling pathway, and the downstream pathways of the mTOR and glycogen metabolic pathways in HG-induced insulin-resistant HepG2 cells." (PMID 31344867, 2019). "It has been suggested that mTOR activation is required for SREBP-1c activity related to lipogenesis, particularly related to insulin-mediated activity in the case of insulin resistance." (PMID 30871035, 2019). "Finally, inhibition of the mTOR (mammalian target of rapamycin) pathway, which was obtained by rapamycin administration through S6 kinase deletion, increases survival and reduces the incidence of age-related diseases, including immune dysfunction and insulin resistance." (PMID 31324014, 2019). "However, regardless of the association of mTOR overactivation and insulin resistance, rapalogs may also cause insulin resistance and hyperglycemia." (PMID 30034573, 2018). "Adiponectin inhibits mTOR/p70S6 kinase pathway by activation of AMPK, thereby contributing to Akt activation and improved insulin resistance." (PMID 29802339, 2018). "Additional studies are needed to further elucidate the potential role of mTOR/SGK1 and INS docking proteins INS receptor substrates 1 and 2 as mediators of the efficacy of SIT on insulin resistance." (PMID 30116740, 2018). "The result being the overactivation of mTOR, and increased inhibitory phosphorylation of IRS-1, leading to insulin resistance." (PMID 29988365, 2018). "Moreover, we hypothesize that galangin and pinocembrin may have a synergistic effect on the improvement of insulin resistance via Akt/mTOR signaling pathway, through distinctly upregulating the phosphorylation of IR, Akt, and GSK3β and remarkably downregulating the phosphorylation of IRS." (PMID 30420897, 2018). "This study indicates that sitagliptin significantly ameliorates the development of hepatic steatosis and insulin resistance in ob/ob mice by inhibiting inflammatory responses and activating autophagy via AMPK/mTOR signaling pathway." (PMID 30123267, 2018). "In our study, we confirm insulin resistance, with de-arranged serum levels of glucose, insulin and ADP, and along this hepatic activation of m-TOR, p-mTOR and Akt was also involved." (PMID 29371918, 2017). "In the models of diabetic nephropathy, especially the type 1, insulin resistance blocks the phosphorylation of Akt/PKB and then activates mTOR by increasing the expression of Rheb (Ras homolog enriched in brain)." (PMID 28512641, 2017).
Insulin resistance (continued). "Previously, we demonstrated that LECT2 increased mammalian target of rapamycin (mTOR) phosphorylation, sterol regulatory element-binding protein (SREBP)-1 cleavage, lipid accumulation, and insulin resistance in HepG2 cells." (PMID 28376109, 2017). "One theory is that an increase in BCAA levels activates the mTOR/S6K1 kinase pathway and results in the phosphorylation of several serine residues in IRS-1, contributing to insulin resistance." (PMID 27249024, 2016). "We, and others, have previously shown that leucine increases mTOR/P70S6K signaling, which can contribute to insulin resistance." (PMID 25996822, 2015). "The multiple physiological consequences of IRS-1 phosphorylations are seen in increased activation of the mTOR pathway along with enhanced phosphorylation of IRS-1 at Ser307 and Ser636/639 that occur in animal models of insulin resistance." (PMID 26474286, 2015). "Proposed mechanisms include reduction of mammalian target of rapamycin (mTOR) signalling by activation of adenosine monophosphate activated protein kinase (AMPK), and decreased insulin resistance." (PMID 26475035, 2015). "Although the kinase activity of MTOR in MTORC2 is insensitive to acute rapamycin treatment, chronic exposure to the drug can disrupt its structure and results in insulin resistance." (PMID 24880909, 2015). "In one hand, leucine activates the mTOR-S6K pathway, which inhibits the insulin receptor substrate 1(IRS1), thus, the over stimulation of this pathway by a high intake of BCAA leads to insulin resistance." (PMID 26217523, 2015). "Recently it was demonstrated that mTOR participates in EGFR signaling in beta cells during glucose and intralipid infusion induced insulin resistance, where the compensatory beta cell mass expansion was stimulated via the EGFR-PI3K-mTOR pathway." (PMID 24695557, 2014). "Thus, mTORC2 disruption, rather than inhibition of mitochondria, causes insulin resistance in rapamycin-treated myotubes, and this system may serve as a useful model to understand the effects of rapamycin on mTOR signaling in vivo." (PMID 22973301, 2012). "In experiments with high fat fed obese rats, activity of the mTOR pathway is elevated in skeletal muscle and leads to inhibitory phosphorylation of IRS1, impaired Akt signaling, and insulin resistance." (PMID 22545721, 2012). "Thus, dietary leucine may inhibit adipose inflammation via mTOR inhibition of NFkB, a transcription factor that has been shown to be an important regulator of adipose tissue inflammation and participant in the development of insulin resistance." (PMID 21731668, 2011). "Additionally, resistin contributes to insulin resistance, which not only reduces muscle glucose uptake but also disrupts anabolic signaling pathways like IGF-1/Akt/mTOR, essential for muscle protein synthesis." (PMID 39983655, 2025). "We also detected increased mTOR expression in GDM HUVECs compared to NG under basal conditions, an adaptation known to negatively regulate the PI3K/AKT pathway and potentially contribute to further insulin resistance." (PMID 41373661, 2025). "Similarly, Rg1 reduces inflammation and insulin resistance, while also activating AMPK and inhibiting mammalian target of Rapamycin (mTOR)-mediated autophagy and apoptosis." (PMID 40432897, 2025). "Glucose-mediated insulin resistance provides a feedback mechanism sometimes independent of the activation of mTOR and it is due to direct phosphorylation and inhibition of IRS-1 by S6 kinase." (PMID 40277891, 2025). "Furthermore, another study reported that exercise‐induced mTOR activation in mice indicated a minimal activation of mTORC1, increased mTORC2, and PK1, which suggests the possible modification of insulin resistance through the action of mTORC2." (PMID 40452790, 2025). "Therefore, the activation of the mTOR pathway, which negatively affects IRS-mediated signaling, is acknowledged as a feedback mechanism potentially contributing to the development of insulin resistance in vivo." (PMID 40362446, 2025).
Insulin resistance (continued). "Additionally, obesity-induced insulin resistance disrupts insulin/IGF-1 signaling, thereby overactivating the PI3K/Akt/mTOR pathway." (PMID 41048699, 2025). "Insulin, a crucial hormone for muscle growth, may be suppressed by insulin resistance, in the state of insulin resistance (IR), the PI3K-Akt-mTOR pathway is impaired, leading to reduced protein synthesis and increased degradation." (PMID 40255379, 2025). "In addition, metabolic disturbances, notably insulin resistance and dysfunction in insulin signaling, contribute to kidney dysfunction through several key signaling pathways, including PI3K/Akt, mTOR, Wnt/β-catenin, JAK/STAT, and NF-κB." (PMID 40698245, 2025). "Conversely, the overexpression or activation of SESN2 has been shown to counteract metabolic dysfunction and protect against diet-induced obesity and insulin resistance by modulating AMP-activated protein kinase (AMPK) and mammalian target of rapamycin (mTOR) pathways." (PMID 40433409, 2025). "Acute activation of mTOR through protein intake and resistance exercise promotes hypertrophy, yet sustained overnutrition and chronic mTOR activity can attenuate AMPK signaling, leading to reduced autophagy, insulin resistance, and impaired cellular maintenance." (PMID 41356921, 2025). "Downstream from mTOR, S6K1 activation has been demonstrated to reduce energy intake and mitigate metabolic perturbations, such as increased fat deposition and the presentation of insulin resistance, even during high-fat feeding in mice." (PMID 41190149, 2025). "In conclusion, our findings indicate that insulin induces insulin resistance in human DPSCs, resulting in impairments in proximal insulin signaling events (INSR, IGF1R, IRS1, and PI3K) while maintaining the activity of distal pathway components (AKT and mTOR)." (PMID 39075596, 2024). "Insulin resistance and hyperglycemia stimulate IGF-1 signaling, and IGF-1 then activates oncogenic signaling pathways such as PI3K/Akt/mTOR, JNK/MAPK, Wnt, and Ras/MEK/ERK, which promote cell proliferation and angiogenesis and inhibit apoptosis, eventually fostering the development of HCC." (PMID 39123380, 2024). "Another possible effect of FST overexpression on muscle is by improving insulin resistance which reinforces insulin’s action and increases insulin-stimulated intracellular insulin signaling of AKT/mTOR that increases protein synthesis and up-regulates muscle mass." (PMID 38409184, 2024). "However, MTOR, AMPK signaling, insulin resistance, nonalcoholic fatty liver disease (NAFLD), and pathways in cancer were uniquely triggered in the female liver due to ancestral BPA exposure." (PMID 38826193, 2024). "ATP surplus induces insulin resistance through several mechanisms, including AMPK inhibition, reactive oxygen species (ROS) production, mitochondrial dysfunction, the mechanistic target of rapamycin (mTOR) activation, and the induction of hyperinsulinemia and hyperglucagonemia as reviewed." (PMID 39873003, 2024). "Immunoblotting showed lower protein levels of Akt/mTOR and phosphorylated insulin receptor substrate 1 (p-IRS1) in ApoE4 mice than in ApoE3 mice, suggesting that ApoE4 led to energy metabolism dysfunction and insulin resistance." (PMID 36720919, 2023). "In cell models, CYP17A1 was found to be involved in glucose metabolism by increasing glucose intake and utilization, through activating IGF1/mTOR/HIF1-α signaling way, which was consistent in CYP17A1 knockout mice with impaired glucose tolerance and insulin resistance." (PMID 37370070, 2023). "Overactive mTOR and its resistance to insulin stimulation are considered pathological features of AD that represent insulin resistance independent of type-2 diabetes, along with impaired insulin receptor function in AD postmortem brain." (PMID 37457922, 2023).